MLLT11 (MLLT11 transcription factor 7 cofactor)
Diseases named in the same sentence as MLLT11 in open-access papers (continued):
Sharing a sentence is not in itself a finding about the gene and the disease.
cancer (22 papers, 2006 to 2024). A tumor composed of atypical neoplastic, often pleomorphic cells that invade other tissues. "Based on the fact that GPRC5A is less studied and lacks its specific association with cancer, we chose MLLT11 for a deeper study." (PMID 38075552, 2023). "Furthermore, we also were able to identify genes such as BRCA1, ABCA1, TNFRSF1B, MLLT11 that have been associated with various types of cancers." (PMID 22594378, 2012). "Consequently, protein expression levels of PI3K, AKT, MMP2, and MMP9 that are the proteins implicated in cancer progression in the siRNA-treated group were significantly decreased, stipulating that the cancer-promoting effect of MLLT11 might be related to the PI3K/AKT signaling pathway." (PMID 38075552, 2023). "The gene BMX nonreceptor tyrosine kinase regulates differentiation and tumorigenicity of several types of cancer cells, and another gene (MLLT11, transcription factor 7 cofactor) was expressed in several leukemic cell lines." (PMID 30793795, 2019). "While two genes, PDZK1 and MLLT11, were clearly relevant to cancer as both have been proposed as a candidate oncogenes in diverse haematological malignancies, 6 were more difficult to relate to cancer." (PMID 17060936, 2006). "MLLT11 has been shown to play a dual function in malignancy, including both promotion and inhibition of cancer progression, and therefore may be relevant in OSCC prognosis and management." (PMID 37245006, 2023).
tumor (17 papers, 2006 to 2023). "It was observed that the expression of pSTAT3 was suppressed in the siRNA and inhibitor groups (activators of CMA, including 6-aminonicotinamide and nutrient starvation), thus suggesting a role for the association of MLLT11 with STAT3 in tumor growth." (PMID 38075552, 2023). "Specifically, a potential Mllt11 interactor Myosin 10 is known to regulate radial migration of CPNs through its effect on the localization of N-cadherin, and has been implicated in tumor invasion by regulating process extension." (PMID 35379703, 2022). "A functional role of MLLT11 in tumor progression was also reported in human breast and endometrial carcinomas, as well as in a number of other human solid tumors." (PMID 38203610, 2023). "Then,MLLT11 expression in tumor samples and normal brain tissues was confirmed by real-time quantitative polymerase chain reaction (qPCR), Western blotting, and immunohistochemistry (IHC) in our institute." (PMID 36033495, 2022). "This is consistent with the expression of bulk tumor sequencing, that is,MLLT11 is mainly upregulated in TCGA-NE and TCGA-PN." (PMID 36033495, 2022). "In contrast to this oncogenic role, in the nervous system, MLLT11 functions as a tumor suppressor, with a high level of expression in normal brain tissues compared with decreased expression correlating with the malignant tumor grade." (PMID 38203610, 2023). "Furthermore, inhibiting MLLT11 led to a significant decrease in the tumor size, which is in line with the outcomes observed in the cell line experiments." (PMID 38075552, 2023). "According to the changes of the expression status of differential molecules between the two networks, we identified the top 10 differential mRNAs (PRKAA2, NLGN4X, ST6GALNAC3, DGAT1, TRIB1, GRPR, and MLLT11) and lncRNAs (n339695, n378130, and n410438) in the tumor–endothelium interaction." (PMID 33681194, 2021). "Moreover,MLLT11 also plays an important role in tumor cell and immune cell interaction in the TME." (PMID 36033495, 2022). "RT-qPCR results showed that the abundance of P4HA1, MLLT11, AURKA, and GOT1 were significantly elevated in tumor tissues." (PMID 35558559, 2022). "We showed that MLLT11, TRIL, and p-AKTThr308 were significantly expressed in tumor tissues compared with the normal endometrial tissues." (PMID 35253622, 2022). "Consistent with the RT-qPCR results, Western blot also showed that the protein levels of P4HA1, MLLT11, AURKA, and GOT1 were markedly higher in the tumor tissues than those in the paratumor tissues." (PMID 35558559, 2022). "Moreover, six paired fresh tumor tissues and paraneoplastic tissues from children with MRTK were collected to validate the expressions of P4HA1, MLLT11, AURKA, and GOT1 in clinical samples via real-time fluorescence quantitative PCR and Western blot." (PMID 35558559, 2022). "Further analysis stratified by tumor grade indicated that there was no statistical difference in the expression ofMLLT11 between the young and old subgroups in LGG, but in GBM,MLLT11 expression in the old subgroup was significantly lower than that in the young subgroup." (PMID 36033495, 2022). "MLLT11 and CCBP2 are both found in tumours, but no other information is available to allow speculation on a possible mode of action for their induction of apoptosis." (PMID 16768789, 2006).
brain disorder (1 paper, 2022). A disease affecting the brain or part of the brain. "Given that Mllt11 mutant mice displayed both migratory and neurite outgrowth defects, they are a model to study brain disorders arising from aberrant regulation of the neuronal cytoskeletal during development." (PMID 35379703, 2022).
neurodevelopmental disorder (1 paper, 2022). A behavioral and cognitive disorder with onset during the developmental period that involves impaired or aberrant development of intellectual, motor, or social functions. "Loss of Mllt11 led to neurite outgrowth defects coupled with loss of UL-specific transcriptional programs characteristic of neurodevelopmental disorders." (PMID 35379703, 2022). "Cortical thinning and increased ventricular lumen surface area are common phenotypes associated with neurodevelopmental disorders, and were observed in Mllt11 mutant brains, suggesting cytoskeletal dysregulation may underlie a subset of these disorders." (PMID 35379703, 2022).
MLLT11 also shares sentences with these, for which no sentence is quoted: endometrial cancer (2 papers); osteosarcoma (2); colorectal cancer (1); COVID-19 (1); endometritis (1); glioblastoma (1); hematological malignancies (1); Huntington disease (1); lung carcinoma (1); male infertility (1); neuroblastoma (1); ovarian tumor (1); Parkinson disease (1); prion disease (1); promyelocytic leukemia (1); thyroid tumours (1).